LEP (leptin)
Diseases named in the same sentence as LEP in open-access papers (continued):
Sharing a sentence is not in itself a finding about the gene and the disease.
Obesity (continued). "In order to assess the MP status in obesity, wild type C57 (wt) or ob/ob mice (leptin ko) explants (from muscle, heart, lung and adipose mass), containing organ specific MPs were taken after surgery." (PMID 19214223, 2009). "In study on NZO mice, obesity correlated with leptin concentration, and the group fed with HF diet, demonstrated hyperleptinemia." (PMID 19344534, 2009). "As a consequence, LY mice exhibit progressive adult-onset obesity, and gradually develop insulin resistance, hyperleptinemia, central leptin resistance." (PMID 19650929, 2009). "This study has confirmed the previous findings demonstrating positive correlations between serum marker of obesity i.e leptin and insulin and left ventricular mass changes." (PMID 19393079, 2009). "Since Leptin is a physiological feedback signal to reduce appetite and thereby should prevent the development of obesity, the occurrence of overweight and elevated circulating leptin concentrations, as seen in OSAS patients, deserves an explanation." (PMID 19946426, 2009). "There are not many clinical studies that were designed to establish a direct relationship between leptin and norepinephrine levels in obesity status." (PMID 21274292, 2009). "Even so, maintenance of normal serum leptin concentrations can be beneficial to prevent leptin resistance and obesity." (PMID 19703309, 2009). "Leptin levels are elevated in proportion to insulin levels, glucocorticoids, cytokines and particularly obesity." (PMID 20066136, 2008). "In this study, BMI was taken as major criteria of obesity and correlation of BMI with different clinical and genetic parameter was seen like waist to hip ratio and hormonal levels (insulin, leptin, glucagon, and growth hormone)." (PMID 20300294, 2008). "A variety of factors have been proposed to explain the obesity-related endothelial dysfunction including alteration in the adipocyte-derived hormones resistin, adiponectin and leptin, high plasma triglycerides concentration and increase of oxidative stress." (PMID 18510739, 2008). "Evidence suggests a role for obesity, leptin and adiponectin in regulating the progression of established cancer." (PMID 21566743, 2008). "FABP4 has been reported as a possible candidate gene for obesity since it was located within a quantitative trait loci (QTL) region contributing to the serum leptin levels in rat." (PMID 19077218, 2008). "Several clinical studies also demonstrated the relationship between obesity, leptin and breast cancer." (PMID 21566743, 2008). "In fact, leptin informs the brain about the size of adipose stores and has been thought to be the obesity hormone regulator." (PMID 18828917, 2008). "At any rate, the state of leptin resistance in common human obesity remains to be completely elucidated, and further studies in this field are awaited." (PMID 21566743, 2008). "Obesity is the major factor regulating circulating leptin which is also influenced by gender and age." (PMID 18828917, 2008). "In this study, the authors found a strong and highly significant positive correlation between obesity (BMI) and serum leptin levels at baseline (p < 0.001) as others have demonstrated." (PMID 18828917, 2008). "Leptin was higher in obesity (8.9 ± 0.6 vs. 4.7 ± 0.6 ng/ml, p < 0.001) and also correlated with aortic measures." (PMID 18275595, 2008). "This study aims to determine and correlate leptin levels to anthropometric measures of obesity in pre-diabetic, (IFG and IGT), type 2 diabetic and normoglycaemic Saudis." (PMID 17617917, 2007). "Serum leptin levels were significantly higher in Obesity-Prone mice compared with Obesity-Resistant (p < 0.01) and Low-Fat (p < 0.001) mice." (PMID 18162139, 2007). "For example, obesity leads to increased leptin and reduced adiponectin; this obesity-induced state of hyperleptinemia and hypoadiponectinemia is associated with increased systemic inflammation and oxidative stress." (PMID 17437645, 2007).
Obesity (continued). "Transient acid exposure and the obesity hormone leptin activated Akt, stimulated proliferation and inhibited apoptosis: the combination of acid and leptin was synergistic." (PMID 17559672, 2007). "Leptin, an adipokine elevated in obesity and known to induce satiety, has been shown to up-regulate various cytokines, promoting a state of chronic inflammation." (PMID 17437645, 2007). "Serum leptin was significantly higher in Obesity-Prone compared with Obesity-Resistant and Low-Fat mice." (PMID 18162139, 2007). "As expected, we found a highly significant trend for increased concentrations of leptin with increasing levels of overweight or obesity (P < 0.0001)." (PMID 17229323, 2007). "We further performed a detailed survey of QTLs for all obesity-related phenotypes such as body weight, fat mass, lean mass and leptin levels." (PMID 17653278, 2007). "In the present study, we used a dietary-induced obesity protocol to further explore the relationship of serum leptin levels and body weight with respect to MT development in MMTV-TGF-α mice." (PMID 18162139, 2007). "A failure of circulating leptin to reach its target receptor within the brain appears to be one mechanism at work in rodents with diet-induced obesity, a classic model of leptin resistance." (PMID 17448988, 2007). "The obesity hormone leptin and short term acid bolus exposure activate Akt in OAC cells in vitro and Akt is essential to the anti-apoptotic and cell proliferative effects." (PMID 17559672, 2007). "Circulating CRP levels are suggested to relate to adipose derived mediators such as leptin and TNFα, and positively correlate with measures of obesity in otherwise healthy adults." (PMID 16965635, 2006). "The associations betweenPPARG and three major influences on BMD, leptin, obesity,and diabetes, are encouraging." (PMID 17347532, 2006). "Obesity has also been shown to increase testosterone and leptin levels, and to depress sex-hormone-binding globulin concentrations." (PMID 16168130, 2005). "For example, with respect to obesity, much recent research has focused on leptin, a hormone released by adipose tissue that regulates appetite by acting on the hypothalamus." (PMID 15885137, 2005). "When SCD1 expression is left unchecked, as occurs in leptin knockout mice, severe obesity can result." (PMID 15719061, 2005). "Obesity can induce a state of leptin and insulin resistance, chronic low-grade inflammation, and increased leptin, tumour necrosis factor (TNF)-α, IL-6 and C reactive protein serum levels." (PMID 16160698, 2005). "Like leptin, adiponectin secretion increases early on in obesity and plays a role in reducing the expression of lipogenic enzymes and increases FA oxidation in peripheral tissues thus limiting ectopic fat accumulation." (PMID 15530168, 2004). "Acquired leptin resistance occurs in aging, obesity, Cushing's syndrome, and acquired lipodystrophy, a condition associated with protease inhibitor therapy of AIDS." (PMID 15530168, 2004). "The present study highlights the importance of shortened sleep in relation to obesity, leptin, and ghrelin, a good start toward this goal." (PMID 15599390, 2004). "The marked elevation of plasma leptin inobese SHR/N-cp rats suggests that obesity in thisanimal model is related to up-regulation of the obgene." (PMID 12369710, 2001). "Although an oversimplification, expression of unwanted weight gain as a consequence of the disease of obesity can most easily be understood as resulting from emergence of leptin resistance, analogous to insulin resistance leading to hyperglycemia and type 2 diabetes." (PMID 41268722, 2026). "Moreover, maternal circulating hepcidin levels showed a strong positive correlation with obesity‐related factors in dams, including maternal body weight, maternal fat mass, maternal leptin and maternal insulin at E13.5." (PMID 41275403, 2026).
Obesity (continued). "Indeed, elevated leptin levels, a surrogate of hyperleptinemia seen in individuals with obesity, markedly enhance the proliferation, migration, and EMT of BC cells through STAT3 activation and NCOA1 upregulation." (PMID 41562922, 2026). "Obesity transforms adipose tissue into a pro-inflammatory endocrine organ, where hypertrophic adipocytes release adipokines such as leptin alongside cytokines including TNF-α and IL-6, potentially contributing to macrophage polarization toward an M1 phenotype and activating NF-κB signaling pathways." (PMID 42188056, 2026). "Leptin levels are typically elevated in obesity and Type 2 diabetes due to leptin resistance." (PMID 41567175, 2026). "Leptin resistance may also exacerbate obesity-related reductions in lung volumes and respiratory system compliance, further increasing mechanical constraints on ventilation." (PMID 41597148, 2026). "Brain leptin signalling plays a central role in the regulation of energy balance and glucose homeostasis, yet its contribution to early metabolic dysfunction preceding overt obesity remains uncertain." (PMID 42097975, 2026). "Leptin-deficient ob/ob mouse demonstrates elevated hypothalamic iron concentration, hinting that iron overload is associated with obesity rather than the nutrient composition of HFD." (PMID 40819297, 2026). "This study therefore can contribute to understanding the importance of leptin as a pubertal and obesity marker in the pubertal timing while highlighting the need to understand the sex-specific mechanisms involved in the link between obesity and puberty." (PMID 41240372, 2026). "The adipokine leptin is produced by adipocytes and levels are elevated in obesity." (PMID 41240372, 2026). "Similarly, BMI serves as an indicator for obesity-mediated renal injury, which operates through glomerular hyperfiltration, leptin resistance, and chronic inflammatory pathways." (PMID 41601932, 2026). "A lack of sleep is known to increase the risk of obesity, insulin resistance, and ghrelin, as well as lower leptin levels, although the influence on plasma cortisol is mixed." (PMID 41515274, 2026). "At the most fundamental level, both obesity medicines and metabolic and bariatric surgery are effective because they treat the disease of obesity by enhancing leptin signaling or leptin sensitivity, manifested when a new homeostatic set point is sustained at a lower, healthier adipose mass." (PMID 41268722, 2026). "However, folate-deficient mice fed a high-fat alone showed smaller increases in serum leptin and hepatic triglyceride levels, suggesting high fructose consumption plays a significant role in obesity, as well documented in the literature." (PMID 41516371, 2026). "In the state of leptin resistance, the metabolic regulatory function of leptin is impaired, but its sympathetic nerve activation effect remains intact, which may indirectly promote the development of obesity-related hypertension." (PMID 41503874, 2026). "An early study reported that activation of the HCRTR2 pathway could combat diet-induced metabolic dysfunction by increasing energy expenditure and improving leptin sensitivity, positioning it as a potential therapeutic target for obesity and related disorders." (PMID 41596924, 2026). "In humans, severe obesity is typically associated with hyperleptinemia, reflecting central leptin resistance rather than deficiency." (PMID 41597148, 2026). "The inability of BPL herbal beverages to inhibit DPP4 activity may indicate that their anti‐obesity effects probably pass through other mechanisms, which inhibit TG absorption and leptin secretion." (PMID 41510340, 2026). "Additionally, both VEGF and IL-6, right after leptin, showed the highest statistical ability in relation to higher blood pressure values in people with obesity." (PMID 41596212, 2026).
Obesity (continued). "Both interventions reduced weight, reversed obesity-induced alterations in insulin, leptin, and inflammatory factors, and decreased tumor incidence and mass, with intermittent energy restriction producing the most favorable antitumor immune and metabolic environment." (PMID 41551882, 2026). "The reductions in leptin, particularly in individuals with obesity, could potentially influence satiety-related pathways, although this hypothesis requires confirmation in studies directly assessing appetite and energy intake." (PMID 42149945, 2026). "Chronic intake of MSG is reported to cause metabolic syndrome or obesity by brain inflammation and leptin resistance, possibly by attacking BBB-lacking brain regions." (PMID 41118118, 2026). "The EPAC2A subtype plays a particularly critical role in this process: EPAC2A knockout mice fed a high-fat diet showed significantly reduced defects in hypothalamic leptin signalling, enhanced suppression of food intake in response to leptin, and a markedly lower incidence of obesity." (PMID 41503874, 2026). "Collectively, these findings support a model in which TRIB1 serves as a critical mediator through which berberine coordinates leptin signaling and mitochondrial function, providing mechanistic insight that may inform future strategies for obesity intervention." (PMID 41588470, 2026). "In obesity, leptin resistance develops, leading to increased serum leptin levels, which may be linked to changes in the BBB observed in obese individuals." (PMID 41562846, 2026). "Interestingly, endometriosis and obesity share similar pathological markers, including leptin, adiponectin, tumor-necrosis-factor-α, and interleukin-6." (PMID 41798441, 2026). "The presence of leptin resistance is a key barrier to the successful management of obesity." (PMID 42318499, 2026). "The treatment of these two cell lines with leptin at 10 ng/mL and 100 ng/mL, concentrations that mimic plasma leptin levels in lean individuals and those with obesity, led to marked overexpression of LEPR in (the more aggressive cell line) MDA-MB-231 cells but not in MCF-7 cells." (PMID 41562922, 2026). "Additionally, HPO axis dysfunction—mediated by leptin resistance, neuropeptide imbalance, and disrupted steroid feedback—links obesity to ovulatory disturbances." (PMID 41239503, 2025). "Leptin, another adipokine elevated in obesity, is known to promote angiogenesis and cell proliferation in BC and may contribute to more aggressive tumor behavior." (PMID 40423926, 2025). "Leptin, on the other hand, regulates satiety and energy expenditure but can promote insulin resistance in the setting of hyperleptinemia and leptin resistance, particularly in obesity." (PMID 41523554, 2025). "However, in obesity, elevated levels of leptin cannot trigger these effects because leptin has become "leptin resistant", adding to further weight gain and metabolic dysregulation." (PMID 40013194, 2025). "The onset of obesity leads to AT remodeling, reducing the release of anti‐inflammatory adipokines (e.g., adiponectin) and increasing the secretion of pro‐inflammatory adipokines (e.g., leptin)." (PMID 40847538, 2025). "Obesity leads to abnormal adipose tissue function, releasing pro-inflammatory cytokines (such as tumor necrosis factor-α and interleukin-6) and adipokines (such as leptin and adiponectin)." (PMID 41343605, 2025). "Key hormones such as leptin, adiponectin, and ghrelin have been implicated in the pathogenesis of obesity, irrespective of their site of secretion or mechanisms of action." (PMID 41423640, 2025). "Additionally, it was also closely associated with several circulating parameters (i.e., glucose, insulin, triglycerides, leptin) in diet-induced obesity (DIO) mice." (PMID 40298780, 2025). "The present study could provide the first evidence in children that EE has additive effects beyond PA alone in reversing leptin resistance in overweight or obesity." (PMID 40607230, 2025).
Obesity (continued). "Elevated leptin levels are commonly observed in individuals with obesity and type 2 diabetes." (PMID 41300847, 2025). "Likewise, leptin, a marker of fat mass that regulates appetite and energy balance, can be elevated in obesity and be a marker of leptin resistance (increased appetite and weight gain)." (PMID 40013194, 2025). "Oxytocin was lower and leptin higher in metabolically unhealthy obesity (both p<0.01)." (PMID 41356005, 2025). "Collectively, these findings suggest that aberrant leptin signaling contributes to functional deficits in VSMCs and highlight a regulatory role of leptin in VSMC phenotypic transformation, a central mechanism underlying obesity-associated macrovascular pathology." (PMID 40940776, 2025). "Women with GD-F and especially GD-M had higher percentages of obesity and excessive weight gain during pregnancy as well as lower high-density lipoprotein cholesterol, higher triglyceride, and higher leptin levels at 6 to 9 weeks after delivery compared with women with GD-P." (PMID 41212558, 2025). "In obesity, the interaction between hypertrophic adipocytes and immune cells, such as macrophages, leads to an overproduction of pro-inflammatory cytokines and adipokines, like leptin." (PMID 40095902, 2025). "Chronic activation of ArcGABA non-LepR neurons led to massive obesity, which was associated with normal leptin-induced pSTAT3 signaling but phenotypic leptin resistance; i.e., high leptin levels failing to reduce obesity." (PMID 40540394, 2025). "The existence of elevated LEP levels in obese individuals has been interpreted as evidence that some cases of human obesity may arise as a result of reduced LEP action in the brain, rendering individuals unresponsive to pharmacological LEP treatment." (PMID 41226484, 2025). "Has been described that leptin’s protective correlation against cognitive decline is observed in non-obese individuals but lost in overweight ones, reflecting midlife leptin resistance in obesity." (PMID 41155642, 2025). "In the case of leptin–ghrelin, there was deregulation of these hormones under conditions of increased adipose tissue that was combined with metabolic alterations in severe obesity." (PMID 41441006, 2025). "In Wistar male rats with HFD-induced obesity, 30-day supplementation with 6-gingerol led to lower body weight, reduced adipose tissue, and decreased levels of leptin, glucose, insulin, and serum lipid profiles compared to the control group, particularly at the dose of 75 mg/kg/day." (PMID 40733199, 2025). "In addition, TRZ can mitigate brain leptin resistance, which is the possible link between obesity and AD." (PMID 40498212, 2025). "The combination of absence of the –759T allele and presence of the LEP –2548G allele was associated with an increased risk of obesity and higher waist circumference WC." (PMID 40507625, 2025). "Leptin, produced by salivary glands, influences taste perception and is affected by obesity." (PMID 41047117, 2025). "Further research is needed to clarify leptin's influence on lung inflammation and its interplay with metabolic disorders like obesity, which could inform targeted therapeutic strategies for ARDS and other pulmonary diseases." (PMID 40635334, 2025). "Moreover, leptin resistance—commonly seen in obesity and metabolic syndrome—further impairs endothelium-dependent vasodilation." (PMID 41470134, 2025). "The insulin resistance and leptin resistance seen in obesity may worsen parameters that reflect thyroid function through various, often unclear, mechanisms." (PMID 39857741, 2025). "Additionally, Oishi and Hashimoto (2018) demonstrated that feeding during the rest phase in mice induces leptin resistance and obesity, underscoring the detrimental effects of feeding–circadian misalignment." (PMID 40649840, 2025). "Biologically, females have lower calorie needs and higher body fat content and leptin levels, which may contribute to the gender difference in obesity prevalence." (PMID 40647318, 2025).